HNRNPK (heterogeneous nuclear ribonucleoprotein K)
Description:
One of the major pre-mRNA-binding proteins. Binds tenaciously to poly(C) sequences. Likely to play a role in the nuclear metabolism of hnRNAs, particularly for pre-mRNAs that contain cytidine-rich sequences. Can also bind poly(C) single-stranded DNA. This interaction is necessary for the induction of apoptosis, but not cell cycle arrest. As part of a ribonucleoprotein complex composed at least of ZNF827, HNRNPL and the circular RNA circZNF827 that nucleates the complex on chromatin, may negatively regulate the transcription of genes involved in neuronal differentiation.
Synonyms: TUNP; HNRPK; CSBP; AUKS
Tractability: PROTAC: UniProt records ubiquitination sites on it; ubiquitination databases record sites on it; its protein half-life has been measured.
Target class: Other nuclear protein
Gene: Protein-coding gene on chromosome 9 (83,966,766 to 83,981,586, reverse strand). Ensembl gene ENSG00000165119.
Subcellular location: Cytoplasm; Nucleus, nucleoplasm; Cell projection, podosome
Subcellular location (Human Protein Atlas): Nucleoplasm
Pathways (Reactome):
Metabolism of RNA: Processing of Capped Intron-Containing Pre-mRNA; mRNA Polyadenylation; mRNA Splicing - Major Pathway
Disease: Dengue Virus-Host Interactions; HCMV Late Events
Metabolism of proteins: SUMOylation of RNA binding proteins
Gene Ontology:
Molecular function: cadherin binding; identical protein binding; protein binding; protein domain specific binding; RNA binding; nucleic acid binding
Biological process: negative regulation of apoptotic process; negative regulation of DNA-templated transcription; positive regulation of low-density lipoprotein particle clearance; random inactivation of X chromosome; regulatory ncRNA-mediated heterochromatin formation; mRNA splicing, via spliceosome; regulation of mRNA splicing, via spliceosome; regulation of transcription by RNA polymerase II; RNA processing; signal transduction; negative regulation of gene expression; regulation of apoptotic process; regulation of DNA-templated transcription
Cellular component: catalytic step 2 spliceosome; chromatin; cytoplasm; extracellular exosome; focal adhesion; membrane; nucleoplasm; nucleus; ribonucleoprotein complex; cytoplasmic stress granule; podosome
Genetic constraint (gnomAD): Loss-of-function variants: 2 observed, 26.05 expected, observed/expected ratio (o/e) 0.0768, 90% interval 0.03 to 0.24. The upper end of that interval is the gene's LOEUF score, 0.24, which puts it in group 1 of 6, group 1 being the genes least tolerant of losing a copy. Missense variants: 147 observed, 304.89 expected, observed/expected ratio (o/e) 0.48, 90% interval 0.42 to 0.55. Synonymous variants: 116 observed, 95.09 expected, observed/expected ratio (o/e) 1.22, 90% interval 1.05 to 1.42.
Gene-disease validity (ClinGen):
ClinGen rates the evidence that HNRNPK causes each of these diseases.
neurodevelopmental disorder-craniofacial dysmorphism-cardiac defect-hip dysplasia syndrome (autosomal dominant): Definitive.
Homologues: Orthologues: chimpanzee HNRNPK (100% identical), dog HNRNPK (100% identical), macaque HNRNPK (100% identical), mouse Hnrnpk (100% identical), rat Hnrnpk (100% identical), tropical clawed frog hnrnpk (78% identical), zebrafish hnrpkl (78% identical), zebrafish hnrnpk (66% identical), Drosophila melanogaster HnRNP-K (40% identical), Caenorhabditis elegans hrpk-1 (37% identical). Paralogues in human: PCBP2 (27% identical), PCBP3 (26% identical), PCBP1 (25% identical), FUBP1 (21% identical), PCBP4 (21% identical), FUBP3 (21% identical), IGF2BP2 (20% identical), KHSRP (20% identical), IGF2BP1 (19% identical), IGF2BP3 (19% identical), NOVA1 (19% identical), NOVA2 (18% identical).
Diseases named in the same sentence as HNRNPK in open-access papers:
HNRNPK is named in the same sentence as 134 diseases in open-access papers, as found by Europe PMC text mining. Sharing a sentence is not in itself a finding about the gene and the disease. The quoted sentences say what the papers report.
colorectal cancer (40 papers, 2006 to 2025). A primary or metastatic malignant neoplasm that affects the colon or rectum. "Elevated levels of EV-associated HNRNPK have also been detected in body fluids from patients with metastatic prostate and colorectal cancers, underscoring its clinical relevance." (PMID 41315767, 2025). "SMYD2 physically interacted with HNRNPK and mediated lysine monomethylation at K422 of HNRNPK, promoting colorectal cancer angiogenesis by stabilizing EGFL7 mRNA." (PMID 40777131, 2025). "U-to-C was initially identified in the mRNA of Wilm’s tumor 1 (WT1) human transcript, while G-to-A was identified in the heterogeneous nuclear ribonucleoprotein K (hnRNP K) protein of colorectal cancer and surrounding tissues." (PMID 36290689, 2022). "Consistent with a role in bone metastasis, knockdown of hnRNPK in prostate cancer PC3 cells abolished the ability of PC3 extracellular vesicles (EV) to induce osteoclastogenesis, and biofluid EV hnRNPK is elevated in metastatic prostate and colorectal cancer." (PMID 33931969, 2021). "We previously reported that the long non-coding RNA (lncRNA) CASC11 promotes colorectal cancer (CRC) progression as an oncogene by binding to HNRNPK." (PMID 33937069, 2021). "By far a number of targets have been reported for G-to-A RNA editing, such as HNRNPK in colorectal cancer and WT1 in cord blood samples." (PMID 34093668, 2021). "For example, heterogeneous nuclear ribonucleoprotein K (hnRNPK), a RBP that plays a role in the nuclear accumulation of lncRNAs, is upregulated in colorectal cancer, gastric cancer and other cancers, and is associated with poor prognosis." (PMID 33854615, 2021). "Our data are in line with a previous study showing that inhibiting ERK1/2 activity by U0126 significantly suppresses the transcription activity of MMP-2 by inhibiting the phosphorylation of hnRNPK and its nuclear translocation in colorectal cancer (CRC) cells." (PMID 30971268, 2019). "G-to-A editing is another alternative editing process, detected in the heterogeneous nuclear ribonucleoprotein K (hnRNP K) protein of colorectal cancer and surrounding tissues." (PMID 31547885, 2019). "MAPK signaling activity confers inherent radioresistance to KRAS-mutant colorectal carcinoma cells by rapidly upregulating of heterogeneous nuclear ribonucleoprotein K (hnRNPK)." (PMID 31138194, 2019). "More recently, another CAM study revealed a decrease in colorectal carcinoma growth and radioresistance upon depletion of hnRNP K (heterogeneous nuclear ribonucleoprotein K)." (PMID 31591362, 2019). "Aberrant hnRNPK expression in the cytoplasm has been reported in pancreatic cancer 15, colorectal cancer 16, prostate cancer 17, and renal cell carcinoma 18, and was associated with poor clinical prognosis." (PMID 27862976, 2017). "In colorectal cancer, studies have found that heterogeneous nuclear ribonucleoprotein K activated the transcription of NUF2, knockdown of NUF2 expression could significantly inhibit proliferation of colorectal cancer cells." (PMID 36670423, 2023). "To further extend this finding, we next examined plasma EVs from a cohort of colorectal cancer patients, as CAV1 has been previously associated with metastatic CRC,41, 42, 43 and hnRNPK has been detected in both EV and membrane raft proteomes of colorectal cancer." (PMID 33931969, 2021). "In addition, another study has found that both nuclear and cytoplasmic hnRNPK significantly increased in patients with colorectal cancer with Dukes’ C staging, which led to adverse clinical outcomes in these patients and to those whose tumors had a low or negative nuclear hnRNPK score." (PMID 33806648, 2021). "In colorectal cancer, the overexpression of lncRNA MEF enhances c-Myc mRNA translational efficiency by interacting with heterogeneous nuclear ribonucleoprotein K (hnRNPK), establishing the MEF-c-Myc regulatory axis as a driver of tumorigenesis." (PMID 41229433, 2025).
colorectal cancer (continued). "The functional role for hnRNPK in PC3 EV‐mediated osteoclastogenesis and EV hnRNPK detection in metastatic prostate and colorectal cancers implicate EV hnRNPK as a potential biomarker for metastatic cancer." (PMID 33931969, 2021). "In addition, circ-GALNT16 can inhibit SENP2-mediated hnRNPK de-SUMOylation by binding to the KH3 domain of hnRNPK and inhibit the progression of colorectal cancer." (PMID 37777749, 2023). "Similarly, high hnRNPK levels were also observed in colorectal adenocarcinoma compared with normal samples (COAD with fold change = 1.574, colorectal carcinoma with fold change = 1.462, and rectosigmoid adenocarcinoma with fold change = 1.215)." (PMID 35875075, 2022). "Additionally, there have already been several researches uncovering the intermediating effects of hnRNPK between lncRNAs and β-catenin, and in detail, lncRNA CASC11 interacted with hnRNPK and then activated Wnt/β-catenin signaling to augment the growth and metastasis in colorectal cancer." (PMID 38111678, 2023).
breast carcinoma (36 papers, 2005 to 2024). "Analysis of clinical data identified an association between the AURKA-YBX1/hnRNPK complex and poor prognosis in breast cancer." (PMID 37415951, 2023). "Taken together, these data demonstrate that the AURKA-YBX1/hnRNPK complex is associated with adverse outcome in breast cancer." (PMID 37415951, 2023). "In conclusion, our study demonstrated that LINC00571 was highly expressed in breast cancer, and promoted cancer cell proliferation through the HNRNPK/ILF2-TCA cycle axis." (PMID 38238853, 2024). "The AURKA-YBX1/hnRNPK complex correlates with poor breast cancer prognosis, and blocking nuclear AURKA shows promise in reversing oncogenic splicing events, highlighting YBX1’s significant role in this process." (PMID 38255791, 2024). "For instance, hnRNPK expression is frequently upregulated in neoplasms such as gastric cancer, hepatocellular carcinoma, and breast carcinoma, implying its contribution to the aggressive nature and rapid proliferation of these tumors." (PMID 39479349, 2024). "We found that the direct interaction between K19 and HNRNPK was required for cytoplasmic HNRNPK localization in the MDA-MB-231 breast cancer cells." (PMID 37592256, 2023). "Analysis of AURKA and hnRNPK protein expression levels in clinical breast cancer samples showed that hnRNPK expression was positively correlated with AURKA expression levels." (PMID 37415951, 2023). "Correlation analysis in GEPIA indicated that AURKA at a high level has linkage to both YBX1 and hnRNPK with increased expression in breast cancer." (PMID 37415951, 2023). "In conclusion, PROX1 exerts its pro-metastasis role in breast cancer by interacting with hnRNPK to activate WNT/β-catenin signaling to promote the invasion and metastasis of breast cancer." (PMID 35342346, 2022). "We investigated the mRNA expression of hnRNPK in breast cancer cell lines with altered PROX1 expression." (PMID 35342346, 2022). "The HnRNP family members HnRNPA1, HnRNPA2, HnRNPI, HnRNPM and HnRNPK have been reported to be highly expressed in breast cancer." (PMID 36052258, 2022). "High hnRNPK expression in breast cancer cells, prostate cancer cells, and melanoma tissues is reportedly accompanied by elevated c‐Myc levels." (PMID 35352475, 2022). "We reported that PROX1 promote metastasis and invasion of breast cancer through the WNT pathway by interacting with hnRNPK which can facilitate β-catenin nuclear translocation." (PMID 35342346, 2022). "Subsequently, we immunolocalized hnRNPK in patients with breast cancer, which revealed that hnRNPK immunoreactivity was significantly higher in ERα-positive carcinoma cells and significantly lower in Ki67-positive or proliferative carcinoma cells." (PMID 33806648, 2021). "hnRNPK directly interacted with ERα and was involved in the ER-mediated signaling pathway in breast cancer." (PMID 33806648, 2021). "Immunoreactivity of hnRNPK, ERα, and Ki67 was detected in the nuclei and counted in more than 1000 breast carcinoma cells." (PMID 33806648, 2021). "First, we studied the expression of hnRNPK using estradiol (E2) and ERα antagonist ICI 182,780 treatment using the ERα-positive breast carcinoma cell line MCF-7 to explore the potential association between hnRNPK and the ER-mediated signaling pathway." (PMID 33806648, 2021). "Heterogeneous nuclear ribonucleoprotein K (hnRNPK) transcripts are abundant in estrogen receptor (ER)- or progesterone receptor (PR)-positive breast cancer." (PMID 33806648, 2021). "In this study, we analyzed the function of hnRNPK as a binding protein in the ER-mediated signaling pathway in breast cancer." (PMID 33806648, 2021). "The non-coding tre-RNA binding with the hnRNPK to inhibit the translation of E-Cadherin, promoting the epithelial to mesenchymal transition of breast cancer." (PMID 31221168, 2019).
breast carcinoma (continued). "RT-PCR was conducted to examine YBX1 and hnRNPK implicated in RNA splicing regulation by virtue of AURKA mediation, which showed that YBX1 knockdown promoted GOLGA4 exon skipping, whereas hnRNPK knockdown promoted RBM4 exon inclusion in breast cancer cells." (PMID 37415951, 2023). "Therefore, we have not only determined how HNRNPK localizes to the cytoplasm but have also identified novel cytoplasmic RNA targets of HNRNPK in breast cancer cells." (PMID 37592256, 2023). "Interestingly, a spike in dsRNA-specific J2 signals was also observed in the breast cancer (BT-549) and lung adenocarcinoma (A549) cell lines following hnRNPK KD." (PMID 36038571, 2022). "Furthermore, PROX1 can interact with hnRNPK to activate WNT/β-catenin signaling in breast cancer cells." (PMID 35342346, 2022). "However, the biological functions of hnRNPK in the ER-mediated signaling pathway in breast cancer have remained virtually unexplored." (PMID 33806648, 2021). "In this study, the immunoreactivity of hnRNPK was detected in the nucleus of breast cancer cells." (PMID 33806648, 2021). "Therefore, the possible interaction between hnRNPK and ER is reasonably postulated to be involved in the ER-mediated signaling pathway of breast cancer." (PMID 33806648, 2021). "Furthermore, our results demonstrated that hnRNPK was mainly expressed in the nuclei of breast carcinoma cells, indicating that hnRNPK functions as a tumor suppressor in breast carcinoma." (PMID 33806648, 2021). "Therefore, this study analyzes the functions of hnRNPK expression in the ER-mediated signaling pathway in breast cancer." (PMID 33806648, 2021). "In addition, hnRNPK transcripts are more abundant in ER- or progesterone receptor (PR)-positive breast cancer or luminal-type cancer." (PMID 33806648, 2021). "This is the first study to demonstrate the immunoreactivity of hnRNPK in breast cancer." (PMID 33806648, 2021). "For example, hnRNPK has been reported to interact with treRNA to enhance breast cancer metastasis." (PMID 31110205, 2019). "In contrast, overexpression of hnRNPK enhances breast cancer cell proliferation." (PMID 21799787, 2011). "Moreover, PROX1 intervenes ubiquitination of hnRNPK in breast cancer cells." (PMID 35342346, 2022). "Furthermore, hnRNPK expression could be an additional target of endocrine therapy in patients with ERα-positive breast cancer." (PMID 33806648, 2021). "Therefore, the interactions between hnRNPK and ERα could be involved in the suppression or inhibition of breast carcinoma cell proliferation." (PMID 33806648, 2021). "Oncogenic AURKA influences breast cancer-related RNA splicing, interacting with YBX1 to promote GOLGA4 exon inclusion and with hnRNPK to induce RBM4 exon skipping." (PMID 38255791, 2024). "PROX1 interacts with hnRNPK to inhibit the ubiquitination of hnRNPK, which in turn activates the WNT pathway to promote invasive metastasis of breast cancer." (PMID 37736108, 2023). "The phosphorylation of hnRNPK at serine 379 increased the expression of migratory molecules β-catenin and matrix metalloproteinase MMP12, thereby enhancing metastasis in the breast cancer cell line MDA-MB-231." (PMID 36982162, 2023). "In breast cancer, PROX1 activates the WNT/β-catenin signaling pathway in conjunction with hnRNPK, leading to cancer cell invasion and metastasis." (PMID 37685269, 2023). "In breast cancer, patients with histological grade III cancer had more hnRNPK proteins than those with lower grades according to an analysis using Western blotting." (PMID 33806648, 2021). "We initially evaluated hnRNPK expression upon treatment with estradiol (E2) and ICI 182,780 in the ERα-positive breast carcinoma cell line MCF-7." (PMID 33806648, 2021). "Among all the RBPs (HNRNPU, HNRNPK, RBM5, HNRNPLL, HNRNPH1, HNRNPM, HNRNPA2B1) screened, only SRSF7 (also known as 9G8) was substantially upregulated in hypoxia-treated breast cancer cells." (PMID 34362878, 2021).
breast carcinoma (continued). "Five out of the six splicing factors have been shown before to be overexpressed in breast cancer: HNRNPA1, HNRNPA2B1, HNRNPK, PTBP1 and SRSF6." (PMID 32756364, 2020). "Binding of hnRNPK and CBFB to RUNX1 mRNA was also detected in several other breast cancer cell lines, indicating that binding of hnRNPK and CBFB to RUNX1 mRNA is a general mechanism." (PMID 31061501, 2019). "In kinase-independent functions, AURKA interacts with heterogeneous nuclear ribonucleoprotein K to activate C-MYC promoter, enhancing breast cancer stem cell phenotypes." (PMID 31254157, 2019). "Correspondingly, in K19 knockout breast cancer cells, HNRNPK does not localize in the cytoplasm, resulting in reduced cell proliferation." (PMID 37592256, 2023). "Moreover, the interaction of PROX1 and hnRNPK inhibits the ubiquitination of hnRNPK, and subsequently activates WNT pathway to promote the invasion and metastasis of breast cancer." (PMID 35342346, 2022). "We calculated the amount of each splicing factor and found that the HNRNPA2B1 level was slightly lower in breast cancer patients and all other splicing factor levels higher; this difference reached significance for PTBP1 (p < 0.05), HNRNPK_ex89 (p < 0.05) and SRSF6 (p < 0.01)." (PMID 32756364, 2020). "Here we found that AURKA could not regulate the expression of hnRNPK, but could recruit hnRNPK to form splicing co-factors that facilitate RBM4 exon skipping in breast cancer." (PMID 37415951, 2023).